ALK (ALK receptor tyrosine kinase)
Diseases named in the same sentence as ALK in open-access papers (continued):
Sharing a sentence is not in itself a finding about the gene and the disease.
lung cancer (continued). "The identification of target gene alterations is an evolution for the lung cancer management, with the combination of tumor genotyping making personalized treatment possible, and it is of great benefit to patients treated with kinase inhibitors (TKIs) for EGFR, ALK, ROS1, BRAF, or MET." (PMID 35600411, 2022). "RET fusion may be responsible for the pathogenesis in patients with lung cancer without mutations in EGFR, ALK, or ROS1, which may be related to the RET-induced promotion of apoptosis resistance." (PMID 35211155, 2022). "However, compared to the results in lung cancer, the partners of the ALK fusions in our study were totally different, and none of them were the canonical type (EML4-ALK)." (PMID 36612279, 2022). "Still, to date, there have been no reports of patients with advanced anaplastic lymphoma kinase (ALK)-positive lung cancer achieving clinical complete response (cCR) in the systemic lesion and pathological complete remission (pCR) in primary lung lesion after multiple lines of conversion therapy." (PMID 36523965, 2022). "In our study, we could not analyze how many ALK-positive patients with lung cancer at baseline developed VTE, but none of the 36 patients who used ALK inhibitors during the follow-up period developed VTE." (PMID 36089919, 2022). "Anti-ALK-directed therapy of ALK + lung cancers does not lead to the disappearance of these cells." (PMID 35902427, 2022). "Due to the fact that ALK rearrangements are rare in lung cancer, most samples will be negative." (PMID 35626451, 2022). "Our findings show that not all ALK-aberrant lung cancer cells exhibit the same propensity to undergo an EMT process, thereby determining whether they are able to acquire multi-resistance to various ALK–TKIs." (PMID 36551587, 2022). "We then questioned whether lorlatinib used at concentrations efficacious against ALK-rearranged lung cancer cells but non-toxic to ALK-negative cells could promote substantial lipidome changes in Huh-7 cells." (PMID 36077379, 2022). "Compared with stage-IIIB/IV lung cancer patients with pan-negative driver mutations (OS 12.3 months), those with mutations of EGFR (OS 22.5 months) or ALK (OS 21.9 months) experienced better OS; while KRAS mutations (OS 6.4 months) were associated with poor OS." (PMID 35713442, 2022). "Treatment options for lung cancers include surgery, chemotherapy, radiotherapy as well as monoclonal antibodies targeting epidermal growth factor receptor (EGFR), anaplastic lymphoma kinase (ALK), programmed cell death 1 (PD-1) and programmed cell death ligand 1 (PD-L1)." (PMID 34765548, 2021). "In recent years, clinical studies have shown that immunotherapy (PD-1/L1 monoclonal antibody, CTLA-4 inhibitor) has great potential in the treatment of lung cancer patients without epidermal growth factor receptor (EGFR) and anaplastic lymphoma kinase (ALK) mutations." (PMID 34587898, 2021). "However, the exact mechanism of poor survival in ALK fusion lung cancer patients without receiving targeted therapy is unclear." (PMID 34234236, 2021). "However, as for ALK(+) lung cancer, some ALK(+) ALCL patients do not respond to crizotinib or an acquired resistance occurs several months following an initial response." (PMID 33466277, 2021). "We further analyzed mRNA expression of 67 genes in 5 ALK-positive lung cancer samples and the corresponding pericarcinous (normal) tissues by NanoString assay, and found increased mRNA of ALK, ROS1, MET, SPP1 and PI3K signaling pathway in ALK-positive lung cancer." (PMID 34234236, 2021). "However, the molecular mechanism of poor outcomes in ALK fusion lung cancer patients who did not receive targeted therapy is unclear." (PMID 34234236, 2021). "Additionally, phosphoproteomic analysis of ALK-positive lung cancer cells with or without gilteritinib treatment revealed that gilteritinib significantly decreased phosphorylation of ALK and its adapter proteins such as IRS1/2, SOS2, or SH2B1." (PMID 33627640, 2021).
lung cancer (continued). "Furthermore, reversing ALK-TKI and inhibiting angiogenesis in combination with alectinib and apatinib, thus inhibits ALK and VEGF R2 controlling the progression of the EML4-ALK fusion gene lung cancers." (PMID 34660278, 2021). "A recently published case report of four ALK-positive lung cancer patients with RBN revealed that all of the patients had seen a decrease in RBN and that three had experienced symptom improvement after bevacizumab (15 mg/kg every 3–4 weeks) was added to their ALK-TKI therapy." (PMID 33842309, 2021). "Cancers such as lung cancer, head and neck cancer, and melanoma have exhibited clinical benefit with IO, although patients who are never smokers (i.e., ALK, ROS, and RET) or whose tumors express mutant EGFR showed 0–14% response rates, irrespective of PD-L1 expression levels." (PMID 34001994, 2021). "Similarly, ALK-positive lung cancers were also observed to have a higher SUVmax than ALK-negative lung cancers." (PMID 31924270, 2020). "In addition, more patients in the ALK mutation group had advanced lung cancers (stages III and IV), distant metastases and no smoking history than those in the ALK wild-type group." (PMID 32266148, 2020). "Moreover, there is a relatively high percentage of AYAs with lung cancer who never smoked and have driver mutations, such as EGFR, ALK, KRAS, and ROS1." (PMID 33218178, 2020). "Furthermore, Met, ALK, APC, PTEN, ERBB4, NF1, and other genes, involving multiple tumor suppressor genes and lung cancer-driven genes, did not mutate in recurrence-free patients when compared with recurrent patients." (PMID 31182981, 2019). "However, in three patients with lung cancer, the GCC2 gene was shown to fuse with anaplastic lymphoma kinase (ALK; MIM #105590), which has a critical role in the pathogenesis of non‐small cell lung cancer, and targeting it with crizotinib was shown to be active against cancer." (PMID 30697976, 2019). "This may partly explain why driver mutations, including EGFR, ALK, and KRAS, were not identified in lung cancer patients." (PMID 31069172, 2019). "Interestingly, LCAT1 was upregulated in a distinct subgroup of lung cancer patients who did not have actionable mutations in EGFR, ALK, ROS or NRAS." (PMID 31779616, 2019). "Even though the relative proportion of NSCLC bearing ALK rearrangements is significantly lower than ALCL or inflammatory myofibroblastic tumors (IMT), ALK-positive NSCLC represent overall the largest cohort of ALK-rearranged patients due the fact that lung cancer has a high incidence worldwide." (PMID 29495603, 2018). "In exactly the same way, rapamycin sensitized crizotinib-resistant EML4-ALK+ lung cancer cells to ALK inhibition: Crizotinib alone did not affect ALK and AKT activity, but blocked the feedback activation from mTOR to AKT, when administered together with rapamycin." (PMID 29755689, 2018). "Thus, ALK inhibition by ceritinib may lead to upregulation of SRC signaling, and AZD0530 could serve as a potential drug in the clinic to treat ALK‐resistant lung cancer patients." (PMID 28396832, 2017). "To date, no report has described correlations between miR-28-5p and lung cancer or the ALK pathway." (PMID 28514730, 2017). "However, a recent phase-II clinical trial of AUY922 in lung cancer patients with ALK rearrangements who had shown disease progression on ALK inhibitors failed to yield a positive outcome." (PMID 28938595, 2017). "We could differentiate between ALK rearrangement-positive and -negative lung cancer samples by comparing sweyjawbu expression." (PMID 28032602, 2017). "We further demonstrated that the second‐generation ALK‐TKI alectinib was much more effective than the first‐generation ALK‐TKI crizotinib in the in vivo imaging model, thus indicating the usefulness of alectinib against brain metastases induced by EML4‐ALK lung cancer." (PMID 29125233, 2017).
lung cancer (continued). "In addition to the ALK rearrangements, other fusion transcripts of the genes for ROS proto-oncogene 1 (ROS1), ret-proto-oncogene (RET) or NTRK genes have been identified in 1–2% of patients with advanced stage lung cancer." (PMID 28805673, 2017). "However, circulating microRNAs in plasma have not been systematically and extensively studied in ALK-positive lung cancer." (PMID 28514730, 2017). "As observed in other studies, our analysis confirms that a high ALK gene copy number gain is not a driver genetic event in lung cancer tumorigenesis but it might represent a marker of chromosome instability, correlated with an aggressive metastatic behavior." (PMID 27561692, 2016). "In summary, our study suggests that ALK FISH may not be the most reliable approach for assessment of ALK gene rearrangement in lung cancer." (PMID 27769042, 2016). "Because the ROS1 and Anaplastic Lymphoma Kinase (ALK) domains are partially homologous, the Food and Drug Administration (FDA)-approved ALK/MET kinase inhibitor crizotinib is being investigated via phase I/II clinical trials for its efficacy in ROS1-driven lung cancer patients." (PMID 25978031, 2015). "As previous studies suggested that the inhibition of ALK and IGF1R pathways may potentiate chemotherapy and radiotherapy in lung cancer, crizotinib might be an effective additional therapeutic agent in patients with aggressive ARMS tumours that overexpress ALK, MET and IGF1R proteins." (PMID 26445453, 2015). "Based on these excellent results of the crizotinib clinical trials and the development of other ALK inhibitors with consistent efficacy results in this patient population, the importance of accurately identifying ALK positive lung cancer has never been greater." (PMID 25248157, 2014). "KIF5B-RET is reported in a low percentage of lung cancers and is more frequent in non-smokers, in patients with adenocarcinoma, and exists exclusively with other mutations, such as EGFR, Kras, Braf, ErbB2 or EML4/ALK fusions." (PMID 25047660, 2014). "Of the 79 ALK-positive lung carcinoma specimens, 32 cases were excluded for lack of tumor tissue." (PMID 25248157, 2014). "Lung cancers without ALK rearrangement sometimes show positivity in highly-sensitive anti-ALK IHC, like iAEP, especially in cases with neuroendocrine differentiation (small-cell, large-cell neuroendocrine, and other carcinomas with focally neuroendocrine differentiation)." (PMID 23936355, 2013). "In addition to TFG-ALK in lung cancer, some ALK fusions have been reported without histopathological evidence: TPM4-ALK in esophageal squamous cell carcinoma and EML4-ALK in colon and breast carcinomas." (PMID 22347464, 2012). "In addition, ALK/MET inhibitor crizotinib also inhibited growth of HCC78- and ROS1-positive tumors suggesting that lung cancer patients with ROS1 rearrangement could benefit from targeted therapy using crizotinib." (PMID 22928112, 2012). "In addition, in a phase II nonrandomized study of the heat shock protein 90 (HSP-90) inhibitor, IPI-504, in patients with advanced lung cancer who previously progressed on EGFR TKI therapy, tumors from 3 patients were retrospectively found to have ALK rearrangements." (PMID 26316937, 2012). "Non–small cell lung cancer harboring a SMARCA4/SMARCA2 deficiency has no established treatment because it is mutually exclusive to genetic abnormalities such as EGFR mutations and anaplastic lymphoma kinase (ALK) and RET fusions, for which there are established treatments." (PMID 39625239, 2025).
lung cancer (continued). "In addition to traditional surgical treatment and chemotherapy, targeted therapies represented by EGFR inhibitors, ALK inhibitors, ROS1 inhibitors and immunotherapies represented by PD‐1/PD‐L1 inhibitors and CTLA‐4 inhibitors are playing an increasingly critical role in the treatment of lung cancer." (PMID 40845073, 2025). "Besides IMT, the ALK gene is subject to genomic rearrangements across a range of malignancies, including anaplastic large cell lymphoma (ALCL), diffuse large B cell lymphoma, glioma, non–small cell lung cancer (NSCLC), colorectal, breast, ovarian, and esophageal cancer." (PMID 39171208, 2024). "In ALK‐rearranged lung cancer, it has been reported that HER3 activation contributes to maintaining cell survival while inducing ALK‐TKI‐DTC occurrence, whereas the treatment with afatinib, a pan‐HER inhibitor, combined with ALK‐TKIs could suppress tumor growth and eventually eliminate DTCs." (PMID 37638338, 2023). "CT features may not correlate with ALK rearrangement in early-stage lung cancer." (PMID 36823653, 2023). "Moreover, some ubiquitination sites on the ATP1A1 and SLC3A2 transporters were upregulated, suggesting that, in ALK-driven lung cancer cells, stabilization of these transporters may not play a significant role in the metabolic changes induced by TKI treatment." (PMID 36996232, 2023). "Second, we focused on the clinicopathological and radiologic features of ALK-positive patients with surgically resected lung cancer in the early stage; therefore, our findings may not be generalizable to patients with ALK rearrangement in the locally advanced or metastatic stage." (PMID 36823653, 2023). "Notably, results of a meta-analysis indicate that lung cancer in non-smokers seems to be a distinct disease caused by mutations in driver genes, such as those for the epidermal growth factor receptor (EGFR) and anaplastic lymphoma kinase (ALK)." (PMID 36358986, 2022). "Thus we concluded that SPP1 overexpression is associated with poor outcomes for patients with ALK fusion lung cancer without receiving targeted therapy and PI3K/AKT/SPP1 pathway may become the promising targets in patients with aggressive lung cancer." (PMID 34234236, 2021). "Therefore, we hypothesized that tumor levels of SPP1 would correlate with poor outcomes in patients with ALK fusion lung cancer who did not receive targeted therapy." (PMID 34234236, 2021). "Understanding heterogeneous TIMEs in ALK rearrangement-positive LCNEC may offer crucial information to optimize the use of immunotherapy, radiotherapy and chemotherapy and may be instructive to discover novel therapeutic approaches for improving the actual cure rate of advanced lung cancer." (PMID 33352665, 2020). "However, the pattern of failure and clinical value of radiotherapy in metastatic crizotinib-treated ALK-mutant lung cancer, with or without baseline brain metastases (BBM), are largely unknown." (PMID 30866974, 2019). "Furthermore, some ALK positive lung cancer patients do not exhibit significant tumor shrinkage with ALK-inhibitor treatment, suggesting refractory residual disease may result from compensatory signaling pathways." (PMID 29507657, 2018). "Consequently, further genetic and molecular studies using next-generation sequencing explored whether MPM involving lung cancer share common molecular targets, such as EGFR, Kirsten rat sarcoma viral oncogene homolog (KRAS) and anaplastic lymphoma kinase (ALK) to improve therapeutic outcome." (PMID 26466785, 2015). "The SEER database does not present molecular markers, including EGFR, ALK, and ROS1, which are critical in guiding the prognosis and therapy for lung cancer BM." (PMID 40098698, 2025).
lung cancer (continued). "Similar to the ALK‐positive subtype, the EGFR‐driven lung cancer is also common for never smokers or light smokers." (PMID 41213866, 2025). "It is not considered useful in ALK‐ and EGFR‐positive lung cancers because most are adenocarcinomas." (PMID 38400801, 2024). "RepID is a crucial player for cell proliferation in driver-negative tumors, including melanoma, breast, and lung cancers which lose HER2, EGFR, ALK, or BRAF expression." (PMID 37461562, 2023). "Of these fusions, 16 (including ALK, ARAF, BRAF, FGFR1, FGFR3, RET, and ROS1) and 21 (including ABL1, GNAS, JAK2, and NRG1) were classified as either related to lung cancer, or as oncogenes that have not been reported in lung cancer, respectively." (PMID 36153311, 2022). "The protein used as an example in the study, anaplastic lymphoma kinase (ALK), is not yet validated and classified as a CTA/TAA at present, but this protein has a potential to be a localized biomarker for lung cancer." (PMID 36620582, 2022). "Although immune checkpoint inhibitors (ICIs) have revolutionized treatment strategies of lung cancer, the overall response rate of ICI monotherapies is still limited and no more than 20% in NSCLC patients with EGFR/ALK wild-type." (PMID 35677561, 2022). "Top-down approaches are exemplified by the discovery of NRF2 activations, which were detected in all lung cancer tissues regardless of the status of other biomarkers, such as EGFR, ALK, ROS-1 and other genetic alterations." (PMID 35806042, 2022). "We also found several recurrent ALK fusions which have not been reported in lung cancer, but have been identified in other cancer types, such as VCL-ALK, FN1-ALK, and NPM1-ALK." (PMID 34508169, 2021). "ALK (EML4-ALK is a well-known fusion oncogene) translocations are more frequent in nonsmokers’ than in smokers’ lung cancer." (PMID 32030321, 2020). "Many laboratories find this easier as lung cancer cases can be batched with other (e.g. colorectal cancer) cases undergoing KRAS testing, rather than waiting for sufficient EGFR or ALK testing samples." (PMID 30470932, 2019). "In contrast to other driver oncogenes in lung cancer, such as EGFR and ALK, molecularly targeted drugs to KRAS have not yet been developed and therapeutic targeting of KRAS-mutated lung adenocarcinoma remains a huge challenge." (PMID 28380052, 2017). "Approximately 85% of lung cancer cases are characterized as non-small cell lung cancer (NSCLC) cases and anaplastic lymphoma kinase (ALK) positive is therein non-negligible, occurring in 2 to 7% of all NSCLC." (PMID 29088872, 2017). "Unlike ALK, there are several mechanisms of resistance that have been reported in EGFR-expressing lung cancer cells and BCR-ABL (breakpoint cluster region-abelson)-expressing chronic myeloid leukemia (CML) cells." (PMID 29143801, 2017). "A recent study tested crizotinib sensitivity in nine lung cancer cell lines and three patients with NSCLC exhibiting ALK CNG, and concluded that HCNG without ALK rearrangement has predictive value for chemo sensitivity to crizotinib." (PMID 26312204, 2015). "The EZR-ROS1 fusion gene was specifically detected in lung cancer specimens of female never-smokers without EGFR, KRAS, and ALK alterations." (PMID 23418494, 2013). "We developed a 5′-rapid amplification of cDNA ends-based system optimized for FFPE tissues and evaluated this system on a lung cancer tissue with ALK rearrangement and without the 2 known ALK fusions EML4-ALK and KIF5B-ALK." (PMID 22347464, 2012). "Companion diagnoses, such as MSI, ERBB2 staining, EGFR, BRAF, ALK fusion, and BRCA1/2, can be done before the standard treatment, which is another reason why the CGP test is not needed, as the drivers of lung cancer, colon cancer, and melanoma are already known to a certain extent." (PMID 36251535, 2023).